HES1 (hes family bHLH transcription factor 1)
Diseases named in the same sentence as HES1 in open-access papers (continued):
Sharing a sentence is not in itself a finding about the gene and the disease.
tumor (continued). "Given its role in cellular proliferation and CRC tumorigenesis and progression, the present study investigated whether tumor expression of Notch target genes, HES1 and ATOH1, may be used as predictors of response to CRT in RC patients." (PMID 34582650, 2021). "In these studies, the decrease in Hes-1 expression by presenilin blockage resulted in PTEN and GSK-3β activation, whereas inhibiting either PTEN or GSK-3β activation increases Hes-1 expression which counteracts their effects on inhibiting tumour cell proliferation." (PMID 34671031, 2021). "Inhibition of the Notch pathway with GSI LSN-411575 has been proven to block NSCLC tumor growth in vivo in Kras murine models, where, in addition to inducing Hes1 downregulation, it affects ERK phosphorylation, inhibits cell proliferation and increases apoptosis." (PMID 32784481, 2020). "The aim of this study was to determine the protein expression levels of Notch1, Hes1,Ascl1, DLL3 in SCLC tumor specimen and the potential association of these biomarkersto platinum chemotherapy sensitivity, prognosis as well as clinical factors in SCLCpatients." (PMID 33104707, 2020). "HES1 represents a critical factor for the maintenance of stem cells, quiescent cells or cancer cells, and has also been demonstrated to elicit drug resistance and metastasis of tumor cells." (PMID 32972441, 2020). "However, recent studies showed that HES-1 was more than a repressor and contributed to cancer stem cell maintenance, cancer metastasis, and tumor multidrug resistance." (PMID 32974155, 2020). "However, no changes were observed in miR-216b expression following the simultaneous over-expression of miR-216b and HES1 in tumor tissues." (PMID 32972441, 2020). "Hes-1 belongs to helix-loop-helix family of the transcription factors and regulates the differentiation of stem/progenitor cells to absorptive cells in intestinal tract or in tumor cells, in addition to the normal cells of gastrointestine." (PMID 31141984, 2019). "This will help us to clarify the role of HES1 in the progression of this neoplastic disease." (PMID 30615540, 2019). "Importantly, HES1 expression in tumor specimens correlated with the expression of stemness-related genes." (PMID 29652830, 2018). "Furthermore, the Notch1 target gene Hes1 was expressed in tumor cells adjacent to CD31-expressing endothelial cells (ECs)." (PMID 29410396, 2018). "Interestingly and importantly, in LGR5+ or DCLK1+ cells of established colorectal tumors, HES1 deletion induced immediate apoptosis, thus consistently reducing the tumor burden." (PMID 29652830, 2018). "Furthermore, in normal LGR5+ cells, HES1 deletion and β-catenin stabilization decreased tumor formation and prolonged host survival." (PMID 29652830, 2018). "In human PC cell lines, the downregulation of PTOV1 induced an upregulation of the endogenous HEY1 and HES1 genes, and reciprocally, the ectopic expression of PTOV1 in PC cells and HaCaT keratinocytes, where Notch acts as tumor suppressor, caused the inhibition of expression of HEY1 and HES1 genes." (PMID 28029646, 2017). "On the other hand, Notch target genes Hes1, Hes5 and Hey2 were expressed with a particular pattern for each gene, with higher Hes1 expression in tumor corticotropes and reduced Hes5 and Hey2 mRNA levels compared with normal pituitary glands, Hey2 being almost undetectable in ATt20 cells." (PMID 28915655, 2017). "Depending on the tumor type, HES1 can either act as oncogene or tumor suppressor." (PMID 28122586, 2017). "This constellation clearly supports the tumor suppressor function of HES1 in MTC." (PMID 28122586, 2017). "The same members and Hes5, instead of Hes1, presented ectopic expression in the tumor parenchyma." (PMID 28086833, 2017). "In addition, DCLK1 also regulates Notch-1 via a miR-144 dependent mechanism and its downstream effector HES1 to promote tumor xenograft growth." (PMID 29246000, 2017).
tumor (continued). "Additionally, analysis of the expression of the target genes Hes1, Hey1 and Hey2 suggested variable activation which differed substantially between clonal cell lines, tumor xenografts and normal pituitaries." (PMID 28915655, 2017). "In the Notch deregulated subset, we observed a high level of expression of the hairy and enhancer of split-1 (HES1) protein (a direct target of the Notch signaling cascade) in most tumor samples tested, suggesting the existence of differentially addicted pathways in these tumors." (PMID 28473715, 2017). "Indeed, among the genes induced by Notch1 in cells and up-regulated in tumors with high Notch1 levels, besides the Notch1 target HES1, we found many genes with tumor-promoting functions." (PMID 27384993, 2016). "Besides, we found Hes1 protein expression were also increased in tumor tissues compared with normal renal tissues." (PMID 27612417, 2016). "Jagged1, ICN1 and Hes1 were expressed in tumor tissue respectively." (PMID 27612417, 2016). "This positive correlation of Notch3 and Hes1 expression (R2 = 0.78, p < 0.001, n = 32) suggests that higher expression levels of Notch3 in the tumor may result in an upregulation of Hes1 gene expression." (PMID 25668819, 2015). "Our data confirmed that tumor-activated TGFβ/Smad1/5 phosphorylation was regulated by synergistic activation of notch and TGFβ pathway by showing that TGFβ and Jag1 were capable of inducing Smad5 phosphorylation as well as Hes1 up-regulation." (PMID 25623554, 2015). "We found that the expression level of Hes1 or MMP14 mRNA was unrelated to the tumor stage." (PMID 26650241, 2015). "In addition, the level of Hes1 gene expression was increased in tumor tissues over that in normal liver tissues in more than 78.1% of the cases (n = 32)." (PMID 25668819, 2015). "The hypoxia-Notch gene subset (HIF-1α/PGK1/VEGF/CA9/OPN-Notch1/Dll1/Hes1/Hes6/Hey1/Hey2) identified by us might hold prognostic implication and offer new opportunities in tumor sub-classification and targeted therapy." (PMID 25734817, 2015). "Another downstream target of Notch1 is Hes1, which contributes to tumor progression." (PMID 25879451, 2015). "We also noticed that the levels of Notch3 and HES1 were both correlated with proliferation markers in these tumors, suggesting that a hyper-activated Notch3-HES1 axis may contribute to tumor aggressiveness in vivo." (PMID 24797362, 2014). "To further investigate whether PTE or/and DAPT regulates Notch1 signaling in vivo, we examined NICD and Hes1 expression in tumor tissues." (PMID 23671619, 2013). "RT-qPCR was also used to assess HES1 mRNA levels in OSA tumor and matched normal bone samples." (PMID 23816051, 2013). "Cytoplasmic HES1 immunoreaction could be observed in tumor cells, but its expression in the basal cells of normal epithelium was absent." (PMID 23409141, 2013). "However, immunohistochemical nuclear staining for HES1 showed that it was over-expressed in the majority of tumor samples." (PMID 23158439, 2012). "Furthermore we studied the effect of GSI treatment on Notch downstream target Hes1 and tumor initiating cell markers CD44 and EpCAM in sorted CD44+/EpCAM+ cells." (PMID 23094026, 2012). "Interestingly, only in tumor 2 (>175×106 cells) were high levels of the Notch target gene Hes1 observed, indicating that Notch signaling accelerates or maintains tumor development once it is initiated by deregulated Wnt-signaling." (PMID 23185135, 2012). "HES1 levels correlated with tumor migration and invasive features of RMS cell lines in vitro, being modest in embryonal subtype cells with low invasive activity, high in highly invasive PAX7-FOXO1 alveolar cells and very high in PAX3-FOXO1 alveolar cells with the highest invasiveness." (PMID 23158439, 2012). "The Tcf1−/− tumor samples were clearly distinguished by factors involved in the Wnt-signaling pathway, Axin2, Lef1, and Tnfrsf19, or in the Notch signaling pathway, Deltex1 and Hes1." (PMID 23185135, 2012).
tumor (continued). "Hes1 may thus act as a tumor suppressor in one context and as an oncogene in another depending on the tumor types and the stages of cancer progression." (PMID 21106062, 2010). "Taken together, it appears that although Hes1 is able to turn on a subset of Notch targets, further enhancement of Notch signaling could provide advantages for tumor growth or survival." (PMID 19688092, 2009). "How does Hes1 potentiate tumor formation by itself and in cooperation with E protein inhibitors?" (PMID 19688092, 2009). "We thank Dr R Kageyama, Kyoto, Japan, for providing HES1 cDNA, Dr T Sudo, Toray Industries Kanagawa, Japan, for providing the HES1 antibody, Professor D Fink, University Hospital Zurich and Professor HJ Altermatt, Berne for their help in collecting tumour samples." (PMID 16136053, 2005). "Since GXYLT2 was previously shown to activate Notch1 signaling by up-regulating Hes family bHLH transcription factor 1 (HES1) to facilitate tumor progression, we investigated whether the suppressive effects of GXYLT2 knockdown on GC aggressiveness were related to Notch1 signaling." (PMID 41492474, 2026). "However, activated and overexpressed Hes1 can play an unexpected anti-tumor role in AML." (PMID 40755759, 2025). "Indeed, a significant positive correlation between HES1 expression and tumor volume (p = 0.0053 and r = 0.9149) was evident in 2OHOA-sensitive tumors, considering the smaller 2OHOA-treated tumors than the smallest tumors in the mice that received the vehicle alone." (PMID 39400678, 2025). "However, the exact mechanism linking aberrant HES1 expression to KRAS/BRAF mutant tumor invasion and metastasis remains unknown." (PMID 37749297, 2023). "Thus, we evaluated tumor infiltrating immune cells in HES1 (+) and HES1 (−) groups." (PMID 37749297, 2023). "Our RPPA analyses determined that the expression of other proteins were affected by PRL-3, including Histone-H3, Chk2, JNK, Hes1, Rictor, Axl, and Hif1-alpha, all of which play known roles in tumor progression, and may represent novel mechanisms by which PRL-3 promotes T-ALL." (PMID 32001668, 2020). "Indeed, DAPT could decrease NOTCH1 and HES1, which indicates that the decrease of tumor size in nude mice by DAPT is an on-target effect." (PMID 27108536, 2016). "However, overall, it is apparent that hypoxic gliomaspheres mimic the in-vivo tumor condition better than the other tissue culture model as the upregulation of Notch genes (Notch1, Notch2, Notch3, Dll1, Hes1, Hey1 and Hey2) is further enhanced upon exposure to hypoxia." (PMID 25734817, 2015). "A marked decrease in Hes1 mRNA expression was observed in both the platinum-sensitive and platinum-resistant PDXs following GSI therapy (data not shown), confirming that this downstream marker of on target effect is also of limited value for associating anti-tumor effect." (PMID 25072022, 2014). "The first one, represented by female V006 showed moderate but widespread Hes1 expression, moderate estrogen receptor staining, undetectable p63 expression, normal E-cadherin distribution, and a marked up-regulation of Ki67 and Hey1 expression in the tumor area." (PMID 23826634, 2013). "We further investigated the roles of Notch1 and Notch2 in MB tumor biology in which their opposite effects have already been reported: Notch1 activity inhibits cell growth and induces apoptosis, while Notch2 up-regulates Hes1 expression, which promotes cell proliferation." (PMID 21931765, 2011). "In the future, it is necessary to delve into the regulatory network of Hes1 in the TME and develop targeted strategies to improve tumor immunotherapy efficacy." (PMID 40755759, 2025). "Notch signaling enhances mTOR pathway activity by inducing the transcription of HES-1, a repressor of PTEN, a tumor suppressor that normally inhibits the PI3K/AKT/mTOR pathway." (PMID 40003637, 2025).
tumor (continued). "In summary, Hes1 plays a central role in the formation of an immunosuppressive TME and tumor immune escape by regulating TAMs, MDSCs, Tregs, immune checkpoints, ECM remodeling, and cancer stem cells, making it a highly promising therapeutic target." (PMID 40755759, 2025). "The multifaceted mechanisms of Notch-Hes1 in malignancies involve EMT, angiogenesis, CSC maintenance, and dynamic tumor-stroma interactions." (PMID 40755759, 2025). "Regulation of HES1 expression by RBPJ was also observed in a human macrophage cell line, THP-1 cells, on treatment with tumor conditioned media from AGS or MB231." (PMID 39702544, 2024). "Tumor-promoting factors, including IL-4, EGF, and TGF-β, induced HES1 expression, but Rbpj knockdown attenuated these responses in both murine and human macrophage cell lines." (PMID 39702544, 2024). "The results showed that the presence of tumor-CM significantly increased binding of HES1, along with STAT6, to the Arg1 promoter, suggesting HES1 directly binds to the Arg1 promoter to lead its expression." (PMID 39702544, 2024). "SPINK13 induces mitochondrial apoptosis and cell cycle arrest by triggering the Notch1/Hes1-PTEN/Akt signaling axis and reversing EMT, thereby inhibiting HCC cell nude mouse xenograft tumor subcutaneous growth." (PMID 39537605, 2024). "Tumor cells were co-cultured with CD8+ T cells isolated from wildtype spleens, along with either BMDMWT or Hes1 cKO." (PMID 39702544, 2024). "Results showed that the high value of regulatory potential between MFAP5 and some of its top predicted NOTCH1/WNT pathway target genes (CCND1, HES1, MYC, RBPJ, NOTCH1, CCN3, CTNNB1 and SOX17) in inferring signaling paths in tumour tissues." (PMID 36855786, 2023). "Our results demonstrated that HES1 was highly expressed in tumor tissues of CRC patients and upregulation of HES1 predicted a worse prognosis." (PMID 37957183, 2023). "Interestingly, metastatic cells cultured on Jag1 expressed higher levels of Hes1, a target gene that has high expression in cells derived from the primary tumors, while exposure to Jag2 increased expression of Hey1 in both primary tumor and metastasis-derived cells." (PMID 37202533, 2023). "Assessment of ASR490 treatment on Notch1 signaling in tumor tissue lysates showed significantly decreased Notch1-NICD and HES1 protein expression in the ASR490-treated groups compared to the vehicle-treated groups." (PMID 36909163, 2023). "HES1+ TAMs and TREM2+ TAMs were preferentially located in the tumor tissue while IL-4I1+ TAMs were enriched at the tumor periphery." (PMID 36845555, 2023). "Compared with colorectal T cells from healthy individuals, the expression of PD-1 and Notch signaling molecules (NOTCH1, NOTCH2, HES1, and HES5) was elevated in tumor-infiltrating CD8+ T cells from CRC patients." (PMID 37131214, 2023). "HES1 has been proven regulated by the NOTCH signaling pathway, along with the Hedgehog and Wnt signaling pathways, which are common pathways of tumor cells and also related to immune response." (PMID 36599974, 2023). "FEZF1-AS1 is a tumor promoter in prostate cancer via Notch signal activation, overexpressed FEZF1-AS1 contributes to higher levels of Notch1, p21 and Hes1." (PMID 36229883, 2022). "To test differences in the concentration of each biomarker between the tumor tissue and the surrounding area, we plotted the median distribution differences (and their interquartile ranges) of NOTCH1, HES1, and THY1 in those areas in the whole population." (PMID 35172861, 2022). "As expected, HES1, HEY2, N-cadherin, and Vimentin expression was increased, and E-cadherin expression was decreased in MDA-MB-231 tumor with BEND5 knockdown." (PMID 35844785, 2022). "Expression study of LGR5, HES1 and ATOH1 were performed by quantitative PCR (QPCR) based on comparative Cq method after normalization to adjacent non tumor tissues and ACTB as a reference gene." (PMID 34582650, 2021).
tumor (continued). "Verince’s group reported that PDAC-derived EVs induced mitochondria-dependent apoptotic pathway in tumour cells through PTEN and GSK-3β activation, and downregulation of Hes-1 expression, a Notch-1 signalling pathway mediator." (PMID 34671031, 2021). "The study detected overexpression of LGR5 and HES1 and down-regulation of ATOH1 in human RC tissues compared to non- tumor tissues." (PMID 34582650, 2021). "Further, ST3Gal IV overexpression increased the Jagged1, Notch1, Hes1, Hey1 and p21 expression, meanwhile, decreased the expression levels of CyclinD1, CyclinE1, CDK2 and CDK4 in xenograft tumor tissues." (PMID 33598419, 2020). "In T‐ALL, the Notch target gene HES1 negatively regulates PTEN expression, which is a tumor suppressor and negative regulator of the PI3K/AKT pathway." (PMID 32274896, 2020). "Of importance, a negative feedback loop of regulation has been reported between miR-199b and HES1, a key Notch effector, then impairing the CD133+ stem cell-like subpopulation of tumor cells." (PMID 27517624, 2017). "HES1 is one of the main genes targeted by NOTCH signaling and plays a critical role in maintaining the stemness of tumor stem cells." (PMID 28881812, 2017). "In accordance, Notch activation was evidenced in AtT20 tumor corticotropes, with higher levels of NOTCH1-3 active domains, Jagged1 and Hes1 compared to normal pituitary." (PMID 28915655, 2017). "NOTCH1, HES1, and p300 expression was significantly higher in HOTAIR-overexpressing xenograft tumours." (PMID 27323817, 2016). "Hes1 mRNA expression and MMP14 mRNA expression were positively correlated in tumor tissue (correlation coefficiency = 0.238, p = 0.035)." (PMID 26650241, 2015). "Although the precise mechanism of tumor suppression by CPEB1 is still undetermined, we found that HES1 and SIRT1 were targets of CPEB1-mediated translational control." (PMID 25216517, 2014). "Tumor tissues were analyzed at single-cell level by immunohistochemistry for the expression of PTOV1, HEY1 and HES1 proteins on serial sections from 20 primary tumors (n = 10 with Gleason < 7 and n = 10 with Gleason > 7) and 16 lymph node metastases." (PMID 24684754, 2014). "The contrasting activities of PTOV1 and HES1 and HEY1 were also tested in HaCaT transformed skin keratinocytes, a cellular model in which Notch has known tumor suppressor functions." (PMID 24684754, 2014). "Knockdown of PTOV1 in PC-3 cells led to a strong upregulation of HES1 and HEY1 both in vitro and in cells implanted in SCID-beige mice, accompanied with a significant delay in tumor growth and metastatic spread." (PMID 24684754, 2014). "RT-qPCR analysis for NOTCH1, NOTCH2, HEY1 and HES1 was conducted on the normal bone/matched OSA and DFI tumor sample sets." (PMID 23816051, 2013). "Increased HES1 mRNA expression was shown in some human OSA cells and OSA tumor samples compared to osteoblasts or normal bone and an association between high HES1 expression and decreased survival of OSA patients has been suggested." (PMID 23816051, 2013). "Expression of human N1C in pre-tumor thymocytes from the ROSA26 locus activated transcription of its known downstream targets such as endogenous Notch1, Hes1, Deltex1, c-myc and Notch3." (PMID 22393458, 2012). "In tissues from inoperable locally advanced and metastatic tumours, nuclear expression of Notch1, -3, -4, HES-1, and HEY-1 (all p≤0.001) was significantly increased compared to expression in resected tumours." (PMID 23226563, 2012). "Compared with the control, SPDCs from tumor-bearing mice had higher level of HES1 and HES5, indicating that Notch signaling was activated in SPDCs of tumor-bearing mice." (PMID 20420708, 2010). "As an initial step to explore this, the relative mRNA level of HES1 and HES5, two major downstream molecules of Notch signaling, in SPDCs was examined in tumor bearing mice." (PMID 20420708, 2010).